NEDD4L (NEDD4 like E3 ubiquitin protein ligase)
Diseases named in the same sentence as NEDD4L in open-access papers (continued):
Sharing a sentence is not in itself a finding about the gene and the disease.
lung cancer (28 papers, 2018 to 2025). A malignant neoplasm involving the lung. "Furthermore, the downregulation of NEDD4L has been implicated in the initiation of breast tumor development, and this gene has been proposed as a prognostic lung cancer marker linked to histological grade, tumor stage, and lymph node metastasis." (PMID 32605588, 2020). "For example, the downregulation of NEDD4L expression in lung cancer cells enhances TGF‐β‐induced EMT to increase metastatic progression." (PMID 39717922, 2025). "M2 macrophage-derived sEVs induced cisplatin resistance in lung cancer by regulating the axis of miR-3679-5p/NEDD4L/c-Myc." (PMID 38362150, 2024). "In A549 lung cancer cells, NEDD4L mediates the ubiquitination and downregulation of GCN2, inhibiting the GCN2-induced apoptosis of cancer cells." (PMID 38027016, 2023). "We then analyzed the relationship between the NEDD4L levels and the prognosis of lung-cancer patients." (PMID 37240137, 2023). "Through our analysis of public data regarding the GEO, TCGA, and CPTAC (Clinical Proteomic Tumor Analysis Consortium) databases, the results show that both mRNA and protein levels of NEDD4L were decreased in patients with lung cancer." (PMID 37240137, 2023). "MiR-3679-5p can be transferred from M2 macrophages to lung cancer cells via the internalization of exosomes, which induces chemical resistance to cisplatin in lung cancer cells through the miR-3679-5p/NEDD4L/c-Myc axis." (PMID 37981718, 2023). "Glutathione peroxidase 4 (GPX4) determines the sensitivity of lung cancer cells to etoposide-induced ferroptosis, and NEDD4L can ubiquitinate GPX4, resulting in its subsequent degradation." (PMID 38027016, 2023). "NEDD4L functions as a tumor-suppressor gene in some cancers, such as breast, pancreatic, and lung cancer." (PMID 37240137, 2023). "MDE were able to promote chemoresistance and aerobic glycolysis in lung cancer through the stabilization of c-Myc by inhibiting NEDD4L." (PMID 38022518, 2023). "For instance, downregulation of NEDD4L occurs in non‐small cell lung cancer and its elevation hampered aggressive tumor biology of cells." (PMID 36052751, 2022). "NEDD4L transcripts exist in many tissues, especially in liver, kidney, heart and lung, and NEDD4L is down-regulated in melanoma, colorectal cancer, lung cancer and other cancers, indicating NEDD4L is a tumor suppressor." (PMID 36091384, 2022). "NEDD4L acts as a tumor suppressor gene and is downregulated in lung cancer, indicating that it has a role in the initiation and progression of lung cancer." (PMID 34743202, 2021). "Although most studies have reported that UBE2T and NEDD4L are involved in the growth regulation of lung cancer cells, their cross-role in the synergistic regulation of cancer cell growth has never been reported before." (PMID 34838005, 2021). "To further characterize the regulation of NEDD4L-induced CPNE1 upregulation in lung cancer cells, we established stable NEDD4L knockout (NEDD4L KO) A549 cell lines." (PMID 34743202, 2021). "MDE was reported to reduce the expression of NEDD4L and then stabilize the c-Myc protein to induce chemoresistance in lung cancer by transferring miR-3679-5p to cancer cells." (PMID 34869021, 2021). "NEDD4L has been reported to be downregulated in multiple types of cancers and acts as a tumour suppressor gene in melanoma, colorectal cancer, lung cancer, and other cancers." (PMID 34330894, 2021). "Further studies demonstrated that NEDD4L suppressed the proliferation, migration and invasion of lung cancer cells." (PMID 34869021, 2021). "Transwell migration and invasion assays showed that NEDD4L knockout promoted lung cancer cell migration and invasion." (PMID 34743202, 2021). "Downregulation of NEDD4L was found in nonsmall cell lung cancer (NSCLC) samples in contrast to those of normal tissues." (PMID 34869021, 2021).
lung cancer (continued). "In the present study, we demonstrated that the exosomes derived from M2 macrophages induce cisplatin-resistance in lung cancer both in vitro and in vivo via a miR-3679-5p/NEDD4L/c-Myc regulatory axis." (PMID 33748098, 2020). "Researchers discovered that in lung cancer, NEDD4L increased Notch2 ubiquitination and degradation." (PMID 39717922, 2025). "NEDD4L acts as an oncogene and is expressed at low levels in tumors such as breast cancer, colon adenocarcinoma, glioma, esophageal cancer, lung cancer, hepatocellular cancer, and endometrial cancer, as it does in ccRCC." (PMID 39596003, 2024). "Functionally, both colony formation and transwell assays supported that overexpression of NEDD4L inhibited the proliferation and metastasis of lung-cancer cells, which could be blocked by overexpression of EGFR." (PMID 37240137, 2023). "Moreover, the downregulation of NEDD4L mediated by miR-3679-5p stabilizes c-Myc, thereby enhancing cisplatin resistance in lung cancer cells." (PMID 38027016, 2023). "NEDD4L mediates the ubiquitination and degradation of c-Myc, a Myc family member, to inhibit cell viability, cell cycle progression, and glutamine metabolism in esophageal lymphoid carcinoma, as well as cellular glycolysis and chemoresistance in lung cancer." (PMID 38027016, 2023). "Furthermore, another study demonstrated miR-93’s oncogenic role in lung cancer by downregulating the expression of NEDD4L." (PMID 36293239, 2022). "But some studies reported that NEDD4L promoted lung cancer cell survival." (PMID 34838005, 2021). "In summary, NEDD4L could inhibit the progression of lung cancer by targeting multiple signaling pathways, but might suppress the apoptosis of cancer cells to a certain extent." (PMID 34869021, 2021). "We further investigated the localization of CPNE1 and NEDD4L in lung cancer cells." (PMID 34743202, 2021). "In lung cancer, NEDD4L was correlated negatively with cell survival and metastasis." (PMID 34838005, 2021). "Moreover, NEDD4L overexpression suppressed tumor cell proliferation, migration, and invasion in nonsmall cell lung cancer." (PMID 34305532, 2021). "This evidence indicated that NEDD4L plays a role in the initiation and progression of lung cancer." (PMID 34330894, 2021). "In order to confirm whether NEDD4L is a target of miR-3679-5p in lung cancer, we transfected A549 cells with miR-3679-5p mimic, then the expression level of NEDD4L was determined by qRT-PCR and western blot." (PMID 33748098, 2020). "Among them, SMURF1, MDM2, SMURF2, TRIM27, and NEDD4L are involved in lung cancer progression." (PMID 33264103, 2020). "Taken together, our findings not only show that M2 macrophage induce chemoresistance in lung cancer through MDE mediated miR-3679-5R/NEDD4L/c-Myc signaling cascade, but also shed the light on the mechanism of the cross-talk between M2 macrophage and lung cancers." (PMID 33748098, 2020). "Taken together, reduction of NEDD4L-mediated c-Myc ubiquitination could be the mechanism by which M2 macrophages promote aerobic glycolysis in lung cancer cells." (PMID 33748098, 2020). "NEDD4L (Neural Precursor Cell Expressed, Developmentally Down-Regulated 4-Like, E3 Ubiquitin Protein Ligase) is a protein-coding gene and the downregulation of it has been proved related to poor prognosis in hepatocellular, ovarian epithelial cancer, lung cancer." (PMID 31775867, 2019). "Therefore, biological function of NEDD4L in lung cancer is still unclear." (PMID 34838005, 2021). "In addition, NEDD4L be involved in the ubiquitination of multidrug resistance-associated protein 1 (MRP1), which was negatively correlated with the prognosis of patients with lung cancer." (PMID 34869021, 2021). "Therefore, the mechanism of NEDD4L in lung cancer remains to be further elucidated." (PMID 34838005, 2021). "Moreover, NEDD4L is suggested to be down-regulated in colorectal and lung cancers." (PMID 29324665, 2018).
lung cancer (continued). "Since EGFR is the key driver of lung cancer and can regulate the expression of various genes, therefore we analyzed the correlation between EGFR and NEDD4L." (PMID 35090513, 2022). "NEDD4L was reported to inhibit TGFβ induced epithelial to mesenchymal transition (EMT) and be related to the prognosis of lung cancer patients." (PMID 35090513, 2022). "Notably, EZH2 could weaken the expression of NEDD4L to serve as an oncogene in lung cancer." (PMID 34869021, 2021). "MiR-93 mediated the decrease in NEDD4L expression and then enhanced TGF-β signaling to activate epithelial-to-mesenchymal transition (EMT) in lung cancer." (PMID 34869021, 2021). "NEDD4L knockout stabilized the CPNE1 protein and enhanced the proliferation and metastasis of lung cancer cells." (PMID 34743202, 2021). "Mechanistically, miR-3679-5p was delivered to lung cancer cells by MDE, downregulating the expression of a known E3 ligase, NEDD4L, which has been identified as a key regulator controlling the stability of c-Myc." (PMID 33748098, 2020). "By identifying the miR-3679-5p/NEDD4L/c-Myc regulatory axis, we provided an insight into how DDP-resistance is developed in lung cancer cells." (PMID 33748098, 2020). "Downregulation of NEDD4L promotes TGF-β-induced EMT, leading to lung cancer metastasis." (PMID 38027016, 2023). "In addition, the protein-expression levels of NEDD4L and EGFR were negatively correlated in lung-cancer cell lines." (PMID 37240137, 2023). "NEDD4L could repress the expression of general control nonderepressible kinase 2 (GCN2) to control its proapoptotic effect on lung cancer cells." (PMID 34869021, 2021). "We also demonstrated that, by inhibiting the expression of NEDD4L in response to MDE, miR-3679-5p could indirectly stabilize the c-Myc protein, which in turn enhances aerobic glycolysis and eventually promotes chemoresistance in lung cancer." (PMID 33748098, 2020). "In addition, JAC4 phosphorylated and stabilized NEDD4L by JWA-triggered activation of the AMPK-signaling pathway; the phosphorylation of NEDD4L further accelerated the degradation of EGFR through enhanced ubiquitination at K716, therefore suppressing the progression of EGFR-driven lung cancer." (PMID 37240137, 2023). "Moreover, immunoblot data showed that among the top five E3 ubiquitin ligases (based on confidence scores in the UbiBrowser database), only NEDD4L could be upregulated by JAC4 treatment in human-lung-cancer cells, which was further confirmed in the JAC4-treated lung-cancer tumor-tissue samples." (PMID 37240137, 2023). "The mRNA level of NEDD4L but not MIB1, WWP1, or other ligases was downregulated in patients with lung cancer." (PMID 37240137, 2023).
colorectal cancer (22 papers, 2013 to 2025). A primary or metastatic malignant neoplasm that affects the colon or rectum. "However, the regulatory role of NEDD4L in IBDs and colitis-associated colorectal cancer (CAC) remains unclear." (PMID 39688910, 2024). "A gene set enrichment analysis (GSEA) of data from patients with colorectal cancer revealed that the activity of the mTOR signaling pathway was negatively correlated with the expression of NEDD4L." (PMID 40279519, 2025). "The screen reveals that neural precursor cell expressed developmentally down‐regulated gene 4‐like (NEDD4L) knockdown promotes colorectal cancer liver metastasis." (PMID 40279519, 2025). "NEDD4L knockdown stabilized PRMT5, resulting in the arginine methylation of AKT1, whereas the overexpression of NEDD4L‐R in NEDD4L‐knockdown colorectal cancer cells promoted PRMT5 degradation to attenuate AKT1 methylarginine levels." (PMID 40279519, 2025). "The effect of NEDD4L inhibits the AKT/mTOR signaling pathway to decrease colorectal cancer cell proliferation, consequently suppressing colonization." (PMID 40279519, 2025). "In colorectal cancer, NEDD4L suppresses tumorigenesis by promoting the ubiquitin-mediated degradation of phosphatase and tensin homolog (PTEN) and forkhead box A1 (FOXA1)." (PMID 41561975, 2025). "The function of NEDD4L related to metastatic colonization was explored since colorectal cancer cells were injected directly into the bloodstream." (PMID 40279519, 2025). "Neural precursor cell expressed developmentally down‐regulated gene 4‐like (NEDD4L) prevents colorectal cancer liver metastasis through ubiquitination and degradation of protein arginine methyltransferase 5 (PRMT5)." (PMID 40279519, 2025). "In this study, we revealed that NEDD4L prevented colorectal cancer liver metastasis and that the metastasis‐inhibiting function of NEDD4L depended on its E3 ubiquitin ligase activity." (PMID 40279519, 2025). "Taken together, the results of our study reveal that NEDD4L decreases the proliferation of colorectal cancer cells to suppress colonization, in turn preventing colorectal cancer liver metastasis." (PMID 40279519, 2025). "The effect of NEDD4L decreased cancer cell proliferation to suppress colonization, and ultimately prevent colorectal cancer liver metastasis." (PMID 40279519, 2025). "The in vitro results revealed that the proliferation of colorectal cancer cells was decreased by NEDD4L, although the epithelial‒mesenchymal transition (EMT), invasion and stemness of the colorectal cancer cells were not affected." (PMID 40279519, 2025). "In this study, we not only revealed that NEDD4L prevented colorectal cancer liver metastasis but also identified a novel mechanism by which NEDD4L affected colorectal cancer liver metastasis." (PMID 40279519, 2025). "This study is the first to show that PRMT5 is a substrate of NEDD4L and reveals not only the metastasis‐inhibiting function of NEDD4L but also a novel mechanism by which NEDD4L prevents colorectal cancer liver metastasis." (PMID 40279519, 2025). "Herein, we demonstrated that both the gene and protein levels of NEDD4L were significantly downregulated in IECs from patients with IBDs and colorectal cancer." (PMID 39688910, 2024). "Y-box-binding protein 1 (YBX1; also known as YB-1) plays a crucial role in tumor metastasis in colorectal cancer, and NEDD4L mediates YBX1 ubiquitination and degradation." (PMID 38027016, 2023). "HIF-1a is ubiquitinated and degraded by NEDD4L to inhibit colorectal cancer angiogenesis and enhance sensitivity to bevacizumab." (PMID 38027016, 2023). "NEDD4L inhibits tumor growth through the proliferation of ubiquitinated proteins and plays an important role in the occurrence and development of colorectal cancer." (PMID 36330132, 2022). "Decreased NEDD4L expression has been found in colorectal cancer (Tanksley, Chen & Coffey, 2013), gastric cancer, ovarian cancer, prostate cancer, and non-small cell lung cancer." (PMID 34458018, 2021).
colorectal cancer (continued). "We also found NEDD4L protein was significantly decreased by western blotting in colorectal cancer samples compared to adjacent normal mucosa." (PMID 24312311, 2013). "Therefore, as a method to avoid the off‐target effect of a single shRNA, NEDD4L‐R, which is resistant to shNEDD4L (TRCN0000000905) targeting, was used to restore NEDD4L expression in NEDD4L‐knockdown colorectal cancer cells." (PMID 40279519, 2025). "Collectively, our findings support the hypothesis that in liver‐metastatic colorectal cancer cells, NEDD4L binds to the PPNAY motif in PRMT5, resulting in the ubiquitination and degradation of PRMT5." (PMID 40279519, 2025). "Moreover, in SW620‐L1 and CT26 cells, which are highly metastatic colorectal cancer cell lines derived from humans and mice, respectively, the overexpression of wild‐type NEDD4L prevented the liver metastasis of cancer cells." (PMID 40279519, 2025). "NEDD4L downregulates and inhibits classical Wnt signaling in colorectal cancer." (PMID 40432804, 2025). "Moreover, low expression of NEDD4L in primary tumors was correlated with poor 5‐year overall survival outcomes in patients with colorectal cancer." (PMID 40279519, 2025). "The screening results revealed that NEDD4L knockdown promoted colorectal cancer liver metastasis." (PMID 40279519, 2025). "Although functional experiments showed that NEDD4L prevented colorectal cancer liver metastasis through PRMT5 degradation to attenuate the methylation of R391 in AKT1, we did not obtain direct evidence that NEDD4L mediated PRMT5 degradation to attenuate the methylation of R391 in AKT1." (PMID 40279519, 2025). "Moreover, the in vivo results revealed that NEDD4L overexpression decreased the proliferation of liver‐metastatic colorectal cancer cells and that NEDD4L knockdown increased the proliferation of liver‐metastatic colorectal cancer cells." (PMID 40279519, 2025). "In the functional rescue experiment, the overexpression of NEDD4L‐R in NEDD4L‐knockdown colorectal cancer cells prevented liver metastasis, suggesting that restoring NEDD4L expression reversed the effect of NEDD4L knockdown on colorectal cancer liver metastasis." (PMID 40279519, 2025). "The effect of NEDD4L decreases colorectal cancer cell proliferation to suppress colonization." (PMID 40279519, 2025). "One study reported that NEDD4L might exert a tumor-suppressive effect in colorectal cancer via Wnt signaling suppression." (PMID 38027016, 2023). "Tanksleyet al. demonstrated that NEDD4L suppresses colorectal cancer by ubiquitylating DVL2." (PMID 35593463, 2022). "In addition, NEDD4L has been shown to act as a cancer suppressor by inhibiting canonical WNT signaling in colorectal cancer (Tanksley, Chen & Coffey, 2013)." (PMID 34458018, 2021). "Indeed, NEDD4L is significantly downregulated at the gene and protein level in colorectal cancer, non-small cell lung cancer and breast cancer amongst others, and is associated with a poor prognosis." (PMID 33282879, 2020). "The role of Nedd4l in colorectal cancer (CRC) remains uncharacterised." (PMID 31867777, 2020). "STK35 is ubiquitinated by NEDD4L and promotes glycolysis by regulating the AKT signaling pathway to affect colorectal cancer chemotherapy resistance." (PMID 38027016, 2023). "NEDD4L can downregulate STK35 via ubiquitination, resulting in apoptosis in colorectal cancer cells." (PMID 38027016, 2023). "14-3-3σ reportedly recruited S448-phosphorylation of NEDD4L to mediate ubiquitination and downregulation of hypoxia-inducible factor-1a (HIF-1a), thereby inhibiting colorectal cancer angiogenesis and enhancing sensitivity to bevacizumab." (PMID 38027016, 2023). "For example, NEDD4L can degrade serine/threonine kinase 35 (STK35) by ubiquitination and subsequently inhibit glycolysis and induce apoptosis of colorectal cancer cells via inhibiting the Akt signaling pathway." (PMID 37580757, 2023).
colorectal cancer (continued). "One report showed that NEDD4L regulated the AKT signaling pathway by ubiquitinating STK35, ultimately affecting chemoresistance in colorectal cancer." (PMID 38027016, 2023). "NEDD4 and NEDD4L E3 ligases control LGR5 receptor turnover in intestinal homeostasis and colorectal cancer." (PMID 31867777, 2020). "Similarly, circNEIL3 recruits NEDD4L to ubiquitinate and downregulate YBX1, thereby inhibiting colorectal cancer metastasis." (PMID 38027016, 2023). "Furthermore, in vivo functional experiments revealed that when PRMT5 was knocked out, NEDD4L knockdown failed to promote colorectal cancer liver metastasis." (PMID 40279519, 2025). "Moreover, we found that the overexpression of NEDD4L prevented colorectal cancer liver metastasis, whereas an E3 ligase activity‐dead mutant of NEDD4L failed to suppress liver metastasis, indicating that the function of NEDD4L depends on its E3 ubiquitin ligase activity." (PMID 40279519, 2025).